HSPA5 (heat shock protein family A (Hsp70) member 5)
Description:
Endoplasmic reticulum chaperone that plays a key role in protein folding and quality control in the endoplasmic reticulum lumen. Involved in the correct folding of proteins and degradation of misfolded proteins via its interaction with DNAJC10/ERdj5, probably to facilitate the release of DNAJC10/ERdj5 from its substrate (By similarity). Acts as a key repressor of the EIF2AK3/PERK and ERN1/IRE1-mediated unfolded protein response (UPR). In the unstressed endoplasmic reticulum, recruited by DNAJB9/ERdj4 to the luminal region of ERN1/IRE1, leading to disrupt the dimerization of ERN1/IRE1, thereby inactivating ERN1/IRE1 (By similarity). Also binds and inactivates EIF2AK3/PERK in unstressed cells. Accumulation of misfolded protein in the endoplasmic reticulum causes release of HSPA5/BiP from ERN1/IRE1 and EIF2AK3/PERK, allowing their homodimerization and subsequent activation. Plays an auxiliary role in post-translational transport of small presecretory proteins across endoplasmic reticulum (ER). May function as an allosteric modulator for SEC61 channel-forming translocon complex, likely cooperating with SEC62 to enable the productive insertion of these precursors into SEC61 channel. Appears to specifically regulate translocation of precursors having inhibitory residues in their mature region that weaken channel gating. May also play a role in apoptosis and cell proliferation. (Microbial infection) Plays an important role in viral binding to the host cell membrane and entry for several flaviruses such as Dengue virus, Zika virus and Japanese encephalitis virus. Acts as a component of the cellular receptor for Dengue virus serotype 2/DENV-2 on human liver cells. (Microbial infection) Acts as a receptor for CotH proteins expressed by fungi of the order mucorales, the causative agent of mucormycosis, which plays an important role in epithelial cell invasion by the fungi. Acts as a receptor for R.delemar CotH3 in nasal epithelial cells, which may be an early step in rhinoorbital/cerebral mucormycosis (RCM) disease progression.
Synonyms: BiP; GRP78; HEL-S-89n
Tractability: Small molecule: a structure with a bound ligand is known; it has a binding pocket of medium quality; it belongs to a druggable protein family. Antibody: UniProt places it where antibodies can reach, with high confidence; UniProt predicts a signal peptide or a membrane-spanning region; its Gene Ontology location is reachable by antibodies, with medium confidence. PROTAC: UniProt records ubiquitination sites on it; ubiquitination databases record sites on it; its protein half-life has been measured; a small molecule that binds it is known.
Gene: Protein-coding gene on chromosome 9 (125,234,853 to 125,241,382, reverse strand). Ensembl gene ENSG00000044574.
Subcellular location: Endoplasmic reticulum lumen; Melanosome; Cytoplasm; Cell surface
Subcellular location (Human Protein Atlas): Annulus; Cytosol; End piece; Mid piece; Principal piece
Pathways (Reactome):
Cellular responses to stimuli: ATF6 (ATF6-alpha) activates chaperone genes; ATF6 (ATF6-alpha) activates chaperones; ATF6B (ATF6-beta) activates chaperones; IRE1alpha activates chaperones; PERK regulates gene expression; Regulation of HSF1-mediated heat shock response
Disease: Dengue Virus Attachment and Entry; Maturation of DENV proteins
Immune System: Antigen Presentation: Folding, assembly and peptide loading of class I MHC; Modulation of host responses by IFN-stimulated genes
Hemostasis: Platelet degranulation
Gene Ontology:
Molecular function: ATP binding; ATP hydrolysis activity; cadherin binding; enzyme binding; misfolded protein binding; protein binding; protein domain specific binding; protein sequestering activity; protein serine/threonine kinase inhibitor activity; ubiquitin protein ligase binding; calcium ion binding; heat shock protein binding; protein folding chaperone; protein-folding chaperone binding; ribosome binding
Biological process: cellular response to glucose starvation; maintenance of protein localization in endoplasmic reticulum; negative regulation of apoptotic process; negative regulation of PERK-mediated unfolded protein response; positive regulation of cell migration; post-translational protein targeting to membrane, translocation; regulation of IRE1-mediated unfolded protein response; substantia nigra development; endoplasmic reticulum unfolded protein response; ERAD pathway; negative regulation of IRE1-mediated unfolded protein response; negative regulation of protein-containing complex assembly; positive regulation of transcription by RNA polymerase II; protein folding in endoplasmic reticulum; protein refolding; regulation of ATF6-mediated unfolded protein response; regulation of PERK-mediated unfolded protein response; regulation of protein folding in endoplasmic reticulum; response to endoplasmic reticulum stress; cerebellar Purkinje cell layer development; cerebellum structural organization; IRE1-mediated unfolded protein response; positive regulation of protein catabolic process; positive regulation of protein ubiquitination
Cellular component: cell surface; COP9 signalosome; cytoplasm; cytosol; endoplasmic reticulum; endoplasmic reticulum chaperone complex; endoplasmic reticulum lumen; endoplasmic reticulum membrane; endoplasmic reticulum-Golgi intermediate compartment; extracellular exosome; focal adhesion; intracellular membrane-bounded organelle; melanosome; membrane; midbody; mitochondrion; nucleus; protein-containing complex; plasma membrane
Genetic constraint (gnomAD): Loss-of-function variants: 14 observed, 43.4 expected, observed/expected ratio (o/e) 0.32, 90% interval 0.21 to 0.5. The upper end of that interval is the gene's LOEUF score, 0.5, which puts it in group 2 of 6, group 1 being the genes least tolerant of losing a copy. Missense variants: 352 observed, 797.37 expected, observed/expected ratio (o/e) 0.44, 90% interval 0.4 to 0.48. Synonymous variants: 258 observed, 302.46 expected, observed/expected ratio (o/e) 0.85, 90% interval 0.77 to 0.95.
Homologues: Orthologues: chimpanzee HSPA5 (100% identical), macaque HSPA5 (100% identical), dog HSPA5 (99% identical), mouse Hspa5 (99% identical), rabbit HSPA5 (98% identical), rat Hspa5 (98% identical), pig HSPA5 (94% identical), zebrafish hspa5 (92% identical), tropical clawed frog hspa5 (91% identical), Drosophila melanogaster Hsc70-3 (81% identical), Caenorhabditis elegans hsp-3 (78% identical), Caenorhabditis elegans hsp-4 (76% identical). Paralogues in human: HSPA8 (64% identical), HSPA2 (62% identical), HSPA1L (62% identical), HSPA1A (61% identical), HSPA1B (61% identical), HSPA6 (60% identical), HSPA9 (51% identical), HSPA4 (33% identical), HSPH1 (30% identical), HSPA4L (29% identical), HYOU1 (28% identical), HSPA14 (27% identical), and 1 more.
Diseases named in the same sentence as HSPA5 in open-access papers:
HSPA5 is named in the same sentence as 458 diseases in open-access papers, as found by Europe PMC text mining. Sharing a sentence is not in itself a finding about the gene and the disease. The quoted sentences say what the papers report.
breast cancer (207 papers, 2008 to 2026). A primary or metastatic malignant neoplasm involving the breast. "In addition, the upregulating protein levels of HSPA5 were mainly responsible for the paraptotic changes associated with ER dilation of breast cancer cells." (PMID 36419652, 2022). "The abnormal overexpression of HSPA5 drived the advancement of breast cancer, liver cancer and various other cancer types." (PMID 40255561, 2025). "Knockdown of HDAC6 increased the acetylation of heat-shock protein 5 (HSPA5) and reduced the ubiquitination and degradation of HSPA5 in breast cancer cells." (PMID 38093179, 2023). "Early studies indicate that TSA prevents the formation of the HSPA5-caspase-7 complex, leading to an increased etoposide-induced apoptosis in breast cancer cells." (PMID 37696842, 2023). "HSPA5 (Heat-shock protein 5) is considered as a marker ofpoor prognosis in breast cancer patients, which plays a critical role in promotingthe drug resistance and metastasis." (PMID 40636894, 2023). "Our research revealed the role of HSPA5 in breast cancer through public databases and comprehensive bioinformatics analysis." (PMID 36193502, 2022). "Heat-shock protein 5 (HSPA5) is regarded as a marker of poor prognosis in breast cancer due to its role in promoting drug resistance and metastasis." (PMID 35216622, 2022). "The positive expression rate of HSPA5 protein in breast cancer tissues was significantly higher than that in the group with lymph node metastasis, suggesting that those with high expression of HSPA5 protein in breast cancer tissues have a poorer prognosis." (PMID 36193502, 2022). "The contributions of HSPA5 have also been shown in breast cancer, in which the HSPA5 knockdown restored the antiestrogen sensitivity in resistant tumor cells by inhibiting apoptosis and stimulating autophagy." (PMID 33902430, 2021). "Hsp90AA1, Hsp90AB1, TRAP1, HspA5, HspB1, HspE1, HspD1, HspA1B, HspA8, HspA9, and HspA4 were validated as potential biomarkers for breast cancer tissue." (PMID 31921692, 2019). "Multiple heat shock proteins, including Hsp90AA1, Hsp90AB1, TRAP1, HspA5, HspB1, HspE1, HspD1, HspA1B, HspA8, HspA9, and HspA4, were significantly upregulated in breast cancer tissue." (PMID 31921692, 2019). "Heat shock proteins showed the most significant change of all the upregulated domains, with Hsp90AA1, Hsp90AB1, TRAP1, HspA5, HspB1, HspE1, HspD1, HspA1B, HspA8, HspA9, and HspA4 identified in breast cancer tissue." (PMID 31921692, 2019). "Previous studies show that HSPA5 inhibits cell migration and invasion in hepatocellular carcinoma, whereas HSPA5 promotes colorectal and breast cancer cells invasion and migration in vitro." (PMID 27034162, 2016). "A recent study further showed that STAT3 mediates cell surface HSPA5-induced human breast cancer MCF-7 cells migration." (PMID 27034162, 2016). "In our study, we demonstrated that E1A significantly decreased HSPA5 expression in three breast cancer cell lines, MDA-MB-231, HBL100 and HS578T cells." (PMID 25301734, 2014). "Mice with HSPA5 haploinsufficiency have decreased mammary tumor growth, development, and metastasis as well as increased survival." (PMID 25301734, 2014). "Elevated expression of heat shock protein 5 (HSPA5) promotes drug resistance and metastasis and is a marker of poor prognosis in breast cancer patients." (PMID 25301734, 2014). "HDAC6 has previously been reported as a deacetylase of HSPA5 in breast cancer cells." (PMID 37696842, 2023). "Interestingly, in contrast to Lyn and Lck, the activity of c-Src was essential for UPR activation (XBP1 and HSPA5 induction) in human breast cancer cell lines revealing differential involvement of SFKs in stress responses." (PMID 37680627, 2023). "Anti-breast cancer drugs were predicted to bind to cs-HSPA5 in stressed cells." (PMID 37275848, 2023).
breast cancer (continued). "It is also suggested that HSPA5, as a new marker for breast cancer, may be a new target for breast cancer treatment, which may provide new ideas for further research on breast cancer." (PMID 36193502, 2022). "Finally, an independent validation showed FNDC1, A1BG, PDIA3, HSPA5, and calnexin as significant prognostic markers for human breast cancer patients." (PMID 34885011, 2021). "The HSP resident in the ER called HSPA5 (GRP78 or BiP) was observed in cell culture medium and cell membrane after ER stress in human rabdomiosarcoma cells (TE671) and breast cancer cells (MCF7) and the ability to secrete HSPA5 has been linked to resistance to the antiangiogenic agent Bortezomib." (PMID 28468249, 2017). "Moreover, recent reports indicate that HSPA5 enhances cells invasion, migration and metastasis in colorectal and breast cancer." (PMID 27034162, 2016). "Additionally, immunoprecipitation (IP) using an anti-HSPA5 antibody followed by an anti-ubiquitin antibody revealed that E1A expression increased HSPA5 ubiquitination in breast cancer cells." (PMID 25301734, 2014). "In this study, we demonstrate that the E1A/p300 interaction inhibits HSPA5 acetylation at K353 and promotes GP78 the E3 ligase-mediated ubiquitination of HSPA5 and its subsequent degradation, which leads to decreased breast cancer cell metastasis in vitro and in vivo." (PMID 25301734, 2014). "Based on the function of HSPA5 as a molecular target in cancer metastasis and progression, we sought to investigate whether HSPA5 was a target of E1A in breast cancer cells." (PMID 25301734, 2014). "We transfected E1A or control expression vectors into a panel of breast cancer cell lines to investigate the effects of E1A on HSPA5 expression and found that E1A suppressed HSPA5 expression and cell migration/invasion in three breast cancer cell lines (MDA-MB-231, HS578T and HBL100 cells)." (PMID 25301734, 2014). "The identified mechanism suggests that targeting HSPA5 for degradation may be a potential therapeutic option for treating breast cancer." (PMID 25301734, 2014). "In addition, high expression of FNDC1 (probe 226930_at, p = 0.019) and the low expression of PDIA3 (probe 227033_at, p = 0.0037), HSPA5 (probe 230031_at, p = 0.0024) and CANX (probe 238034_at, p = 0.0013) were also associated with a worse overall survival in breast cancer patients." (PMID 34885011, 2021). "P300 also catalyzes the acetylation of HSPA5 at K353 to inhibit its degradation mediated by E3 ubiquitin-protein ligase GP78 and promotes breast cancer metastasis." (PMID 35216622, 2022). "This compound results in the activation of ElF2A, HSP90B1/GRP94, HSPA5 and DDIT3 in HepG2 hepatoma and breast carcinoma MCF-7 cells." (PMID 36497321, 2022). "Apparently, HSP1A and HSPA8 are expressed in all breast cancer subtypes; HSPA2 is higher in luminal, while HSPA5 and HSPA6 are higher in basal subtypes." (PMID 34943954, 2021). "Accordingly, in our study, the low gene expression of calnexin, HSPA5, and PDIA3 had a significant prognostic value for OS and DMFS in human breast cancer patients." (PMID 34885011, 2021). "The review is dedicated to the role of members of the heat shock protein 70 subfamily (HSP70s or HSPA), mainly inducible HSP70, glucose-regulated protein 78 (GRP78 or HSPA5) and GRP75 (HSPA9 or mortalin), in the development and pathogenesis of breast cancer." (PMID 34943954, 2021). "The 78-kDa glucose-regulated protein (GRP78), also known as BiP and HSPA5, is highly expressed in many types of cancers, including lung, hepatocellular cancer, and breast cancer." (PMID 30931255, 2019). "Deacetylation of heat-shock protein 5 (HSPA5) by histone deacetylase-6 (HDAC-6) is followed by Gp78-mediated ubiquitination of HSPA5, leading to suppression of invasion and migration in breast cancer cells." (PMID 28890687, 2017).
breast cancer (continued). "Of twenty-three tumor types with available matched normal samples in TCGA, all except three (THCA, KICH, and KIRP) showed greater expression of HSPA5 (the gene coding for GRP78 the master regulator of the UPR), which is also a predictor of resistance to chemotherapy in breast cancer." (PMID 35237269, 2022). "By analyzing heterogeneous intratumor subpopulations and metastatic sites, we demonstrated that FNDC1, A1BG, CANX, HSPA5, and PDIA3 may be key factors to tumor malignancy in a canine model of breast cancer." (PMID 34885011, 2021). "In addition, even the triple knockdown of HSPA1A/B, HSPA5, and HSPA2 expression did not decrease the viability of breast cancer MDA-MB-468 cells." (PMID 32987811, 2020).
hepatocellular carcinoma (112 papers, 2007 to 2026). A malignant tumor that arises from hepatocytes. "Conversely, another study have reported that downregulation of HSPA5 is found to enhance cancer metastasis in hepatocellular carcinoma." (PMID 27034162, 2016). "Interestingly, GRP78/HSPA5 is a universal therapeutic target for hepatocellular carcinoma and chronic liver disease." (PMID 37156995, 2023). "Meanwhile, a case-control study showed that HSPA5-rs430397 effectively predicted the primary hepatocellular carcinoma and liver fibrosis, which also complemented our study hypothesis and results." (PMID 36686460, 2022). "HSP90B1 is proposed to be associated with poor survival from hepatocellular carcinoma (HCC), whereas high levels of HSPA5 and HSPA6 may be associated with earlier recurrence of HCC." (PMID 31101113, 2019). "HSPA5 (GRP78) activates the Wnt/HOXB9 pathway to promote invasion and metastasis of hepatocellular carcinoma by chaperoning LRP6." (PMID 34918006, 2022). "HSPA5 and HSPA8 were in the center of the PPI network, suggesting that they are involved in the occurrence and development of hepatocellular carcinoma via several mechanisms." (PMID 34059060, 2021). "GRP78, also known as HSPA5, is reported to be involved in ER stress and overexpression of many types of human cancers, such as hepatocellular carcinoma, esophageal cancer, gastric cancer and prostate cancer." (PMID 33014334, 2020). "HSPA5 overexpression increases the activity of focal adhesion kinase (FAK) and promotes the invasion of hepatocellular carcinoma cells both in vivo and in vitro." (PMID 25301734, 2014). "Secreted HSPA5 also activated EGFR signaling and conferred the resistance of hepatocellular carcinoma (HCC) cells to sorafeinib." (PMID 37189349, 2023).